SOX2 (SRY-box transcription factor 2)
Diseases named in the same sentence as SOX2 in open-access papers (continued):
Sharing a sentence is not in itself a finding about the gene and the disease.
breast cancer (continued). "Moreover, enhanced interactions between YAP/TAZ, YAP/SOX2 and TAZ/SOX2 were observed in the ALDH+ cells of mice mammary tumors." (PMID 39979255, 2025). "SOX2 has been shown to enhance the growth and spread of cancer cells in various types of tumors, including prostate cancer, lung cancer, laryngeal cancer, cervical cancer, liver cancer, and breast cancer." (PMID 39976818, 2025). "One notable example is the STEMVAC trial, a DNA plasmid-based vaccine encoding five antigens [Mouse Double Minute 2 Homolog (MDM2), YBX1, SRY-Box Transcription Factor 2 (SOX2), Cell Division Cycle 25B (CDC25B), Cluster of Differentiation 105 (CD105)] associated with breast cancer stem cells." (PMID 39727969, 2024). "Recent research in breast cancer has revealed that clusters of circulating tumour cells (CTCs) with metastatic potential exhibit hypomethylation of stemness-related transcription factors, including SOX2, NANOG, OCT4, and SIN3A." (PMID 38920995, 2024). "Additionally, high expression of SOX2 significantly enhances the growth and invasion of ovarian cancer, breast cancer, and hepatocellular carcinoma cells." (PMID 38879516, 2024). "SOX2 was reported to promote breast cancer through targeting miR-181a-5p and miR-30e-5p/TUSC3 axis." (PMID 38864530, 2024). "Furthermore, tangeretin exhibits the potential to inhibit the formation of breast cancer stem cells (BCSCs) by acting on the Stat3/Sox2 signaling pathway, offering a potential therapeutic strategy for breast cancer and BCSCs." (PMID 38998484, 2024). "In breast cancer, the overexpression of SOX2 upregulates CCL3 and ICAM1 via activating NF-κB." (PMID 38331879, 2024). "Moreover, CDDO-Im was shown to effectively block the EGFR/signal transducer and activator of transcription 3 (STAT3)/Sox-2 signaling pathway and consequently metastasis of breast cancer." (PMID 36982173, 2023). "In addition, a recent study demonstrated that in hypoxic conditions, SOX2 expression increases in a time-dependent manner facilitating hypoxia-induced breast cancer cell migration via expression of NEDD9, which further induced Rac1 and HIF-1α expression." (PMID 37614497, 2023). "Moreover, Sox2 knockdown-dependent cell cycle arrest and a decrease in tumoroids have been shown in glioblastoma and breast cancer." (PMID 37853437, 2023). "For example, in breast cancer, the most common markers used in the isolation of the stem-like cells include CD44highCD24low populations, as well as populations that demonstrate high levels of ALDHhigh activity and SOX2 expression." (PMID 36980879, 2023). "Moreover, the purified phenol amine molecule reduced the viability of breast cancer cells at a lower concentration with a significant decrease in SOX-2 expression." (PMID 37542193, 2023). "Also, this molecule significantly downregulated the expression of the pluripotency gene, SOX2 (p < 0.001), and caused the overexpression of CASP3 (a marker of late apoptosis) (p < 0.01) in all breast cancer cells." (PMID 37542193, 2023). "However, consistent data appeared in two ER(+) breast cancer cell lines, and chemical G9a inhibitor decreased SOX2 protein levels." (PMID 36971192, 2023). "Moreover, the overexpression of MALAT1 in breast cancer stem cells (CSCs) influences the stem cell-like phenotypes by modulation of SOX2." (PMID 36726376, 2023).
breast cancer (continued). "Furthermore, SOX2 promotes the migration of breast cancer cells by inducing the expression of neural precursor cell expressed developmentally down-regulated protein 9 (NEDD9)." (PMID 37511298, 2023). "Moreover, miR-203 and miR-150 can regulate the expression of DNMT3A and DNMT3B in breast cancer cells, resulting in regulation of CD44, ALDH1A3, OCT3/4, SOX2 expression, which are critical for breast cancer stem cell development." (PMID 35620052, 2022). "We also analyzed the relationship between the mRNA levels of FGFR2, ERBB4, RET, FN1, MMP16, and SOX2 and tumor stages in breast cancer using GEPIA and found that the levels of FGFR2 were significantly upregulated in stage I and remained stable across stages II–X." (PMID 36601474, 2022). "A subsequent study showed that HOTTIP increased the expression of pluripotency markers octamer-binding transcription factor 4 (OCT4) and SRY-box transcription factor 2 (SOX2), and, in this way, it facilitated the stemness of breast cancer cells by regulating the miR-148a-3p/Wnt1 pathway." (PMID 35328609, 2022). "Also, study demonstrated that MALAT-1 affects the stem cell-like phenotypes in breast cancer cells through regulation of Sox-2." (PMID 36685962, 2022). "Furthermore, curcumin significantly inhibited stem cell-like properties by reducing CD44+CD24− cell subpopulation, the expression of Oct4, Nanog and Sex determining region Y-box 2 (Sox2) in breast cancer MCF-7 and MDA-MB-231 cells." (PMID 36009200, 2022). "Also, SOX2 over-expression increases the proportion of breast cancer stem cells by activating the Wnt signalling pathway." (PMID 36566021, 2022). "SOX2 expression significantly and selectively promotes metastasis to the brain in breast cancer." (PMID 35737114, 2022). "Moreover, the authors observed that silencing Sox2 in breast cancer cells led to a delay in tumour formation in mice xenografts." (PMID 35326385, 2022). "Interestingly, ActD was recently shown to specifically downregulate SOX2 expression in breast cancer and glioblastoma, SOX2 being a key regulator of stem cells’ self-renewal capacity, associated with glioblastoma aggressiveness and poor prognosis." (PMID 35565259, 2022). "Since the transcription activity of TWIST1 and SOX2 in ESCs and breast cancer cells can be modulated through their binding to the promoter region, we hypothesized that a similar scenario may happen in ESCC." (PMID 36553636, 2022). "Furthermore, the expression of NANOG, OCT3/4, SOX2 by CTCs in breast cancer is directly related to disease progression." (PMID 35820816, 2022). "(2018), which demonstrated the upregulation of SOX2 in TAM-R breast cancer cells." (PMID 36601474, 2022). "Furthermore, we demonstrate that tumor activated macrophages induce enrichment of CSCs and expression of CSC specific transcription factors such as Sox-2, Oct-3/4 and Nanog in breast cancer cells." (PMID 35300689, 2022). "But the important role of SOX2 in CSC functions has not only been reported in breast cancer; silencing SOX2 in glioblastoma tumour-initiating cells drastically decreases their proliferative and tumourigenic potential, and SOX2 controls tumour initiation in squamous cell carcinoma." (PMID 36566021, 2022). "Mammospheres or breast cancer cells in hypoxia have higher expression of the KLF4, NANOG, OCT4, and SOX2 genes and CD44 and CD24, which encode pluripotency factors that are required for the maintenance of cancer stem cells, embryonic stem cells, and induced pluripotent stem cells." (PMID 34830821, 2021).
breast cancer (continued). "The previous findings, with the presence of high Sox2 levels in endocrine-resistant breast cancer, suggest that Sox2 could represent a prognostic factor for tamoxifen resistance development." (PMID 34567804, 2021). "In addition, Sox2 downregulation in breast cancer and glioma cells results in decreased proliferation by cell cycle arrest." (PMID 34195082, 2021). "Consistent with our genomic comparison between primary and metastasis, the ESR1 mutation is found by the mean SHAP value as the most predictive feature of metastatic breast cancer, followed by FGFR4 mutation, SOX2 amplification, ERBB2 mutation, and FGFR1 mutation." (PMID 34795255, 2021). "Interestingly, Sox2 and Sox9 have been shown to be critical for the persistence of quiescent stem-like breast cancer cells." (PMID 33985544, 2021). "SOX2 is a developmentally important TF which impacts the progression of breast cancers." (PMID 34988459, 2021). "In addition, lnc408 expression was positively correlated with the protein level of stemness marker (e.g., CD44 and SOX2) in both breast cancer cells and clinical samples." (PMID 33934099, 2021). "We tested whether expression of either Klf4 or Sox2 was affected in BK5.ATF3 mammary tumors using RT-qPCR and found that both Klf4 and Sox2 were significantly upregulated (p < 0.005) in tumors with lower MiR145 levels." (PMID 33652981, 2021). "In addition, the CSCs-related transcription factors Octamer-binding transcription factor 4 (Oct4), SRY-Box transcription factor 2 (Sox2), and Nanog were expressed in all breast cancer cell lines." (PMID 34217266, 2021). "In addition, oestrogen receptor α signalling pathway can downregulate the expression of miRNA-140, and the target of miRNA-140 to regulate the initiation of breast cancer cells is the transcription factor Sox2." (PMID 33628799, 2021). "Indeed, SOX2 expression is adequate to induce mammosphere formation and promotes tumor growth in a xenograft model of breast cancer." (PMID 34066153, 2021). "Moreover, the mRNA and protein levels of representative breast cancer stemness markers, including SOX2, Nanog, and CD44 were notably decreased in the lnc408-knocked down cells compared to their scrambled control cells (sh Ctrl)." (PMID 33934099, 2021). "Similarly, miR-590-5p and miR-140 acted as tumor suppressors and inhibited breast cancer stemness by targeting the SOX2 gene, and both led to reducing the BCSC population." (PMID 34360879, 2021). "Targeting and inhibiting SOX2 is clinically relevant as high SOX2 mRNA levels are positively correlated with decreased overall survival and progression-free survival in patients affected with breast cancer." (PMID 34502261, 2021). "To test this hypothesis, we here investigated the ability of iadademstat to target SOX2-driven CSC in breast cancer, an unexplored cancer type for iadademstat-based therapy." (PMID 32191225, 2020). "In breast cancers, SOX2 is up-regulated by the transcription factor FOXO1 (Forkhead box protein O1), the long non-coding RNA SOX2OT (SOX2 overlapping transcript), and the EGFR/Stat3 signaling pathway in a paracrine manner involving tumor-associated macrophages." (PMID 33553286, 2020). "Additionally, loss of ci-miRNA-101 levels in breast cancer, inhibit apoptosis by upregulating SOX2 levels, thus, promoting breast cancer growth, proliferation and migration." (PMID 32942528, 2020).
breast cancer (continued). "Increased expression of SOX2 correlates with poor prognosis in stage I lung adenocarcinoma, esophageal squamous cell carcinoma, gastric carcinoma, small-cell lung carcinoma, breast cancer, testicular tumors, and ovarian carcinoma." (PMID 32493501, 2020). "In breast cancer, SOX2 increases cell proliferation, colony formation, and cell metastasis." (PMID 33375053, 2020). "One potential mechanism could be β-catenin-driven, as it was shown to bind and regulate the transcriptional activity of Sox2 in a small subset of breast-cancer cells." (PMID 33302540, 2020). "Accordingly, SOX2 might play a driver role in the development of their less differentiated/stem cell-like phenotypic traits characteristics of the basal-like breast cancer phenotype." (PMID 32191225, 2020). "Furthermore, Sox2 is increased in tamoxifen-resistant breast cancer cells and negatively correlated with ERα expression." (PMID 33234169, 2020). "However, knockdown of Sox2 or VEGF counteracted the effect of Snail-mediated endothelial generation by breast cancer cells, indicating that Snail increased blood vessel formation through Sox2 and VEGF." (PMID 32541667, 2020). "By comparison in breast cancers, such associations are not significant, but Sox2 expression is associated with axillary lymph node metastasis, which is a step further than lymphovascular invasion." (PMID 33553286, 2020). "Poorly differentiated human breast cancers tend to express an “embryonic stem cell-like” signature that contains activation targets of Nanog, Oct4, Sox2, and c-Myc, and it has been demonstrated in the MCF-7 breast cancer cell line that Sox2 up-regulates 145 genes, and down-regulates 41 genes." (PMID 33553286, 2020). "We next tested whether the mechanism of action of iadademstat to specifically target mammosphere-forming CSC-like cells might be due to a more general phenomenon involving drivers of breast cancer stemness other than SOX2." (PMID 32191225, 2020). "Considering that PGR (the PR-encoding gene) is a direct ER target gene, and FOXA1 is a critical pioneer factor for ER, it can be hypothesized that Sox2 altered ER transcriptional activity in FMCs of the present study as it does in breast cancers." (PMID 33553286, 2020). "Snail increased the Sox2 promoter activity of the reporter with mutated site B, but not with mutated site A in breast cancer cells, suggesting Snail bound to site A to increase Sox2 promoter reporter activity." (PMID 32541667, 2020). "We hypothesized that the overexpression of Sox2 leads to changes in the expression of proteins related to breast cancer cell adhesion." (PMID 32290242, 2020). "Besides MYC itself, we find upregulation of other breast cancer stem cell factors (SOX2, SOX18, THY1, EYA1, GLI2, SALL1, GLIS1, CXCR4), suggesting that MYC HME cells adopt a stem-like state." (PMID 31942031, 2020). "SOX2 expression is correlated with the prognosis of some human cancers such as non-small cell lung cancer and cervical cancer with better prognosis and breast cancer and gastric cancer with worse prognosis." (PMID 32104175, 2020). "In breast cancers by comparison, the negative association between Sox2 and PR has been described by some authors, but was not significant in a meta-analysis." (PMID 33553286, 2020). "SOX2 methylation is associated with several types of cancer, including small-cell lung cancer (SCLC), squamous cell carcinoma (SCC), glioblastoma, endometrial, and breast cancer." (PMID 32098209, 2020). "At threshold >0% for positivity, it is estimated that 9–33% of breast cancers are Sox2-positive." (PMID 33553286, 2020). "Moreover, we demonstrated that SOX2 feedback inhibits FOXO3a expression by directly transactivating DNMT1, and inhibition of DNMT activity suppressed tumor growth via regulation of FOXO3a/FOXM1/SOX2 signaling in breast cancer." (PMID 31296961, 2020). "This could have therapeutic implications, as it suggests adding cancer immunotherapy to Sox2-targeted therapy for Sox2+ mammary cancers." (PMID 33553286, 2020).
breast cancer (continued). "Fourth, we finally evaluated the clinical relevance of iadademstat as a novel anti-SOX2 epigenetic breast cancer therapy by assessing its ability to impact both the expression of SOX2 and the tumorsphere-forming capacity of CSC-like cells derived from breast cancer patient-derived xenografts (PDX)." (PMID 32191225, 2020). "In addition, our results indicate that the overexpression of H19 and miR-675 observed in cancer cells is accompanied overall with an overexpression of different stem cell markers such as Sox2, Oct3/4 and Abcg2 in breast cancer cell lines." (PMID 32610610, 2020). "Since Snail promoted the expression of the master tumor initiation gene Sox2, we also detected whether Sox2 regulated the endothelium generation of breast cancer cells, and found high Sox2-expression modestly induced the generation of breast cancer cells." (PMID 32541667, 2020). "Some malignant tumors such as breast carcinoma depend on SOX2 for their tumor-initiating ability." (PMID 32191225, 2020). "Here, we hypothesized that Sox2 expression could be involved in the particularly aggressive clinical behavior of invasive mammary carcinomas in cats." (PMID 33553286, 2020). "This suggests that Sox2-positive mammary carcinomas may have a growth advantage over Sox2-negative ones, or that Sox2 expression is acquired or positively selected during local tumor growth." (PMID 33553286, 2020). "Notably, the previous study has shown that nanog acts as the downstream effector of sox2 in breast cancer 24; this result is consistent with our results in this work." (PMID 31420918, 2019). "Our results highlight the essential role of SOX2 in breast cancer cell motility." (PMID 31462898, 2019). "To explore the role of SOX2 in mediating hypoxia-induced cell migration, we first tested whether hypoxia induced SOX2 expression in breast cancer cells." (PMID 31462898, 2019). "This evidence is supported by a report that showed that SOX2 could increase CSC formation in breast cancer cells." (PMID 31885625, 2019). "Our results provide evidence that SOX2 is closely related with breast cancer cell migration in hypoxia and suggest it might be developed as a therapeutic target for breast carcinoma metastasis." (PMID 31462898, 2019). "Furthermore, genetic ablation of eIF4A in TNBC cells resulted in a decrease in breast cancer stemness (reduced expression of SOX2, OCT4, and NANOG levels) mirroring the level of eIF4A." (PMID 31867270, 2019). "Targeting of SOX2 with miR-590-5p can inhibit breast cancer cell stemness and metastasis." (PMID 31462898, 2019). "AKT can stabilize SOX2 in breast carcinoma cells and CSCs seem to be dependent on AKT signaling." (PMID 31731811, 2019). "The role of AKT and SOX2 in breast carcinoma was evaluated in zebrafish." (PMID 31731811, 2019). "Results of gain and loss-of-functional assays revealed that LINC00511 promotes sphere-formation, stem factor (Oct4, Nanog, SOX2) expression, and contributes to the maintenance of breast cancer CSC characteristic, indicating the role of LINC00511 in breast cancer cell stemness." (PMID 30482236, 2018). "This may be linked to Notch signaling as Sox2 is activated by Notch1 ICD in TNBC, and Notch signaling mediates paclitaxel and tamoxifen resistance in colon and breast cancer cells." (PMID 30388742, 2018). "The correlation of SOX2OT and SOX2 was also found in breast cancer tissues." (PMID 29849506, 2018). "Moreover, it was reported that miR-590-5p suppressed CSC-like properties via regulating SOX2 expression in breast cancer cells." (PMID 29549343, 2018). "Expression of proteins involved in cellular reprogramming (including octamer-binding transcription factor 4 (Oct4), sex determining region Y-box 2 (Sox2) and Nanog) has been observed in many different types of cancer, including glioma, pancreatic, lung, prostate and breast cancer." (PMID 30388742, 2018).